EIF3D (eukaryotic translation initiation factor 3 subunit D)
Diseases named in the same sentence as EIF3D in open-access papers (continued):
Sharing a sentence is not in itself a finding about the gene and the disease.
infection (7 papers, 2014 to 2024). The state of being infected such as from the introduction of a foreign agent such as serum, vaccine, antigenic substance or organism. "Western blot analysis of eIF4E-containing complexes by m7GTP-Sepharose enrichment from infected cells confirmed the loss of eIF3D and eIF4GII, as well as the impact of infection on eIF4AII expression." (PMID 28087593, 2017). "At approximately 100 days of infection, only eIF3d was markedly decreased in RPs compared with chronic progressors (CPs)." (PMID 31118081, 2019). "Based on these findings concerning HIV infection, it is possible that eIF3d in the host cells infected by HIV virus inhibits the infection or replication of the virus possibly by inhibiting translation of the viral RNAs, whereas the virus counteracts the inhibition by cleaving eIF3d." (PMID 36997088, 2023). "In addition to processing viral proteins, HIV-1 protease cleaves several human proteins during infection, such as the eukaryotic translation initiation factor 3 subunit D (eIF3D)." (PMID 24271400, 2014). "Moreover, eIF3d may play an important role in infectious diseases and assist infection by viruses such as severe acute respiratory syndrome coronavirus 2 (SARS-CoV-2)." (PMID 36997088, 2023). "Upon infection, the expression of EIF2A, EIF3D, EIF4G1, and EIF4A was increased." (PMID 38674742, 2024).
EIF3D also shares sentences with these, for which no sentence is quoted: lung adenocarcinoma (3 papers); non-small cell lung carcinoma (3); mesothelioma (2); acquired immune deficiency syndrome (1); Acute hepatitis (1); acute myeloid leukaemia (1); benign ovarian cystadenoma (1); bile duct cancer (1); brain tumors (1); colon adenocarcinoma (1); ductal breast carcinoma in situ (1); endometrial adenocarcinoma (1); gastrointestinal tumor (1); genetic disorders (1); kidney cancer (1); liver cancer (1); liver diseases (1); preeclampsia (1); prostate adenocarcinoma (1); rectal cancer (1); serous cystadenocarcinoma (1).